GIP (gastric inhibitory polypeptide)
Diseases named in the same sentence as GIP in open-access papers (continued):
Sharing a sentence is not in itself a finding about the gene and the disease.
type 2 diabetes (continued). "However, when using novel, highly specific assays, the secretion of both GIP and GLP-1 does not appear to be systematically different in those with type 2 diabetes." (PMID 37430117, 2023). "Given the obvious differences in these confounders between healthy individuals and those with type 2 diabetes, there does not seem to be a fundamental difference in how GIP and GLP-1 influence glucagon secretion in healthy individuals compared with those with type 2 diabetes." (PMID 37430117, 2023). "Univariate analyses of the associations between AUCsRAGE 0–240 and AUC0–240 for glucose and the glucose regulating hormones insulin, glucagon, GLP-1, and GIP showed strong negative relationships between sRAGE and GLP-1 in individuals with type 2 diabetes, both during OGTT and IIGI at the 75 g dose." (PMID 32987824, 2020). "GLP-1 is similar to but unlike GIP, actions of GLP-1 are better preserved in type 2 diabetes mellitus (T2DM) patients, which makes it a highly desirable target for drug discovery for T2DM;." (PMID 37287751, 2023). "In the current study, we here determined active GIP, GLP-1, and glucagon levels in type 2 diabetes mellitus (T2DM) subjects with or without DPP-4 inhibitor treatment to characterize the cell-based, receptor-mediated bioassays in comparison to immunoassays." (PMID 32390941, 2020). "Therefore, GIP receptor (GIPR) agonism has not been pursued in the treatment of type 2 diabetes, but novel GLP-1/GIP receptor agonists may soon redefine the pharmacological role of GIP." (PMID 31443356, 2019).
diabetes (267 papers, 2009 to 2026). "Two potential mechanisms have been proposed to explain the loss of GIP function: a reduction in beta cell mass due to the progression of diabetes and glucotoxicity or a decrease in GIP receptor (GIPR) expression on beta cells." (PMID 41575482, 2026). "This variant is associated with several body fat traits, coronary artery disease, and diabetes in the GWAS catalog, consistent with GIP’s function and suggesting a causal role for this variant in these clinical phenotypes." (PMID 38307861, 2024). "Loss of GIP action is therefore associated with a better outcome in diabetes and resistance towards DIO in mice, but contradictory a transgenic overexpression of GIP also promotes resistance to DIO and leads to a reduced fat mass in mice." (PMID 37957462, 2023). "Among HF patients, elevated Gal-4 levels were notably linked with existing diabetes and higher glucose levels, along with the incretin GIP." (PMID 37985679, 2023). "Whilst others have demonstrated decreased or increased GIP intestinal cell density post-surgery, our findings argue against the idea that diabetes amelioration after RYGB is due to loss of EECs secreting the hormone GIP or other hormones from the BPL." (PMID 37228045, 2023). "GIP has been linked to the pathogenesis of diabetes mellitus, and our analyses suggest a potential link to ADHD." (PMID 36151371, 2022). "GIP is the main incretin hormone in healthy people, causative of most the incretin effects, but the insulin response after GIP secretion in type 2 diabetes mellitus (T2DM) is strongly reduced." (PMID 34819089, 2021). "Agonists of the receptor for the GLP-1 have proven successful for the treatment of diabetes, since they reduce the risk for cardiovascular and renal events, but the possible application of GIP as therapy for T2DM is discussed." (PMID 35054422, 2021). "As expected, we saw strong associations between insulin, GIP, and PP and self-reported diabetes after correction for multiple comparisons." (PMID 28753646, 2017). "Analysis restricted to the NHL and lung cancer studies, from which all specimens analyzed were collected at baseline, revealed similar associations between self-reported diabetes and insulin and GIP." (PMID 28753646, 2017). "The strong associations between self-reported diabetes and insulin, GIP, and PP found in this study are biologically expected given the critical roles that they play in glucose transport and metabolism." (PMID 28753646, 2017). "While the exact mechanisms behind the loss of GIP's insulinotropic action in diabetes remains obscure, several lines of experimental evidence suggest that GIPR is substantially down-regulated in pancreatic β-cells under a persistent hyperglycemic condition." (PMID 22536426, 2012). "The study did report a positive association of the GIPR SNP with HDL but no results was provided for association analysis of biochemical parameters in diabetes and SNPs in GIP." (PMID 20673334, 2010). "In contrast, GIP protein expression was significantly higher in the OB+/DM− group (9.46 ± 4.27 pg/mL) than in OB+/DM+: patients (4.03 ± 2.91 pg/mL; P = 0.026), indicating a potential diabetes-associated reduction in jejunal GIP content." (PMID 41561152, 2025). "This may indicate diabetes-associated upregulation of GIPR in the jejunal muscle in response to reduced tissue GIP levels, as demonstrated in the present study." (PMID 41561152, 2025). "This localized, direct paracrine activity has generated considerable interest in understanding how physiological and pharmacological concentrations of GLP-1 and GIP may influence key tissues implicated in the pathophysiology of conditions such as diabetes." (PMID 41561152, 2025). "Further clinical studies are needed to clarify whether GIP-based therapy could actually reduce the risk of cardiovascular events in diabetes patients." (PMID 39273671, 2024). "Interestingly, in this study, we found Gal-4 to be significantly associated with GIP, as well as with diabetes." (PMID 37985679, 2023).
diabetes (continued). "This perpetuating cycle may also explain how the overabsorption of nutrients might increase GIP to such levels that it would overstimulate insulin secretion that would potentially cause insensitivity and diabetes." (PMID 35224107, 2022). "We hypothesized that increased gut‐derived dopamine in diabetes could cause diabetic bone abnormalities by antagonizing the GIP signaling pathway in osteoblasts." (PMID 31687648, 2019). "The present identification of GIP deficiency in RFX6 PTV heterozygotes is in keeping with the murine data showing that GIP expression and secretion is regulated by Rfx621, and, importantly, identifies the first human form of diabetes associated with decreased GIP secretion." (PMID 29026101, 2017). "This loss of GIP’s incretin effect could be either a consequence or a cause of diabetes." (PMID 41575482, 2026). "In addition to these associations, higher levels of insulin, gastric inhibitory polypeptide, and pancreatic polypeptide remained significantly associated with self-reported diabetes with a false discovery rate <5%, indicating that the assay was able to detect markers associated with diabetes." (PMID 28753646, 2017). "There was some evidence for the carbohydrate last meal pattern lowering insulin levels and increasing GLP-1 and GIP levels in individuals with diabetes." (PMID 42045803, 2026). "Both animal and human studies have examined the influences of GIP analogs on bone in diabetes mellitus." (PMID 41596254, 2026). "Tirzepatide is a novel long-acting glucagon-like peptide-1 (GLP-1) and glucose-dependent insulinotropic polypeptide (GIP) receptor agonist that is on the market as a treatment for diabetes." (PMID 42165019, 2026). "The results demonstrated that GIP antagonism for 50 days significantly improved insulin sensitivity and facilitated the reversal of glucose intolerance and diabetes." (PMID 40214973, 2025). "Genetic determinants—including receptor polymorphisms (receptors of GLP1 and GIP), transcriptional regulators (TCF7L2), monogenic diabetes genes, and epigenetic modifications—profoundly influence the entero-insular axis in children." (PMID 40649920, 2025). "In conclusion, to our knowledge, this is the first large-scale study to identify an association between GLP-1 RAs or GLP/GIP RA and an increased incidence of SIBO compared to other second-line diabetes medications." (PMID 40941750, 2025). "GLP-1 agonists development has revolutionized the treatment of obesity and diabetes mellitus, animal studies showed that tirzepatide (a dual GLP-1/GIP-agonist) is superior to bariatric surgery in weight reduction and diabetes remission." (PMID 40822483, 2025). "Tirzepatide, a dual GIP/GLP‐1 receptor agonist for diabetes, suppresses colorectal cancer growth by targeting glucose metabolism." (PMID 40125821, 2025). "An international group of experts in diabetes treatment recently published a consensus report on the use of GLP-1 RAs or novel dual GIP/GLP-1 RA tirzepatide as an adjunctive therapy to AID systems in adults with T1D." (PMID 40004833, 2025). "DPP-IV inhibition preserves the proinsulin activity of GLP-1 and GIP, thus enhancing glucose homeostasis in diabetes." (PMID 39272487, 2024). "The report highlights the need for increased vigilance regarding allergic reactions to new diabetes medications, particularly in the context of GIP/GLP-1 receptor agonists." (PMID 38298324, 2024). "Patients with diabetes exhibit hyperglucagonemia and compromised β-cell function despite significantly higher glucose dependent insulinotropic polypeptide (GIP) levels." (PMID 39202522, 2024). "Taken together, these data indicate that chronic stimulation of K cell Gs signaling potently counteracted the development of hyperglycemia in a mouse model of diabetes, most likely via GIP-mediated stimulation of insulin secretion." (PMID 39436694, 2024).
diabetes (continued). "The lowest levels of GIP and PP concentrations were found in the PDAC patients with NOD or pre-diabetes and weight loss > 2 kg (p < 0.001)." (PMID 39596226, 2024). "The dual GIP/GLP-1 receptor agonist tirzepatide is among the furthest developed multi-agonists for diabetes care and has so far displayed promising nephroprotective effects." (PMID 38472620, 2024). "This was because the function of GIP in the pathophysiology of diabetes was historically questionable." (PMID 37526853, 2023). "We wanted to find out how the GLP-1/GIP dual agonist tirzepatide affected diabetes’s impairment of spatial learning memory." (PMID 37701028, 2023). "In mice, inactivation of the GIP receptor was associated with improved outcomes after experimental myocardial infarction, whereas GIP infusion was found to exert significant anti-atherogenic effects in mouse models of diabetes." (PMID 37542009, 2023). "Regarding the potential effect of incretins in the pathophysiology of diabetes mellitus (DM), both GIP and GLP-1 bind to their specific receptor on the pancreatic cells, GIPR and GLP-1R, which are part of the family of G protein-coupled receptors." (PMID 36834796, 2023). "Further evidence has increased the understanding of GIP showing that GIP likely still has a role in diabetes despite normal or sometimes elevated concentrations." (PMID 37526853, 2023). "Tirzepatide was the first dual GIP/GLP-1R agonist to be approved for the treatment of diabetes in the United States as a novel glucose-lowering medication." (PMID 37096236, 2023). "In recent years, tirzepatide has become the first dual GIP/GLP-1R agonist approved for the treatment of diabetes mellitus in the United States as a new hypoglycemic medicine." (PMID 37096236, 2023). "This enhancement of glucagon secretion, which was also confirmed in healthy subjects and subjects with T2DM, hinders the clinical use of GIP agonists for diabetes treatment." (PMID 37729025, 2023). "Compared with GLP-1, no GIP receptor agonist is utilized clinically to date because the glucoregulatory effects of GIP shows to be weakened in individuals with diabetes." (PMID 35557850, 2022). "GLP-1 and GIP are incretins that play important role in regulating blood glucose and reducing complications in patients with diabetes." (PMID 35571083, 2022). "There is currently a great deal of controversy over the physiopathological impacts of pharmacologically targeting GIP in the context of weight management, as well as for its therapeutic potential during diabetes, metabolic syndrome, and obesity." (PMID 35017517, 2022). "Using this model an obvious strategy was to combine activity for GLP-1 with that of glucose-dependent insulinotropic polypeptide (GIP) to treat diabetes." (PMID 36050763, 2022). "It should be highlighted that GIP levels were independently related to PAD after multivariable adjustment not only for diabetes, but also for CAD, age, sex, BMI, hypertension, and smoking." (PMID 35205155, 2022). "MiR‐197‐3p can regulate glucose metabolism by suppressing PCSK1/3 to inhibit GIP and GLP‐1 production, incretin hormones implicated in the pathogenesis of diabetes." (PMID 34984856, 2022). "Healthy subjects reported a higher hunger score during GIP infusion, only when compared with the placebo, whereas patients with diabetes, during co-infusion, reported a stronger desire to eat." (PMID 35054422, 2021). "Diabetes related biomarkers: GIP, GLP-1, leptin, glucagon and inflammatory cytokines: IL-4, IL-5, IL-10, IL-12, IFN-g and TNF-α were significantly affected by HFB diet compared to HF diet." (PMID 34441468, 2021). "Diabetes related biomarkers, gastric inhibitory polypeptide (GIP), leptin, glucagon, and inflammatory cytokines interleukin 4 (IL-4) and IL-5, 10 and 12, IFN-g and TNF-α were significantly affected by HFB diet." (PMID 34441468, 2021).
diabetes (continued). "In contrast to the case of GLP-1, no GIP receptor (GIPR) agonist is clinically utilized to date because its therapeutic potential was doubted by the observations showing impaired insulinotropic effects of GIP in individuals with diabetes." (PMID 32098413, 2020). "We also did a set of analyses wherein we excluded all diabetic individuals (prevalent and incident diabetes cases) in the MDC-CC cohort, with associations between GIP and mortality risk essentially unchanged." (PMID 31974732, 2020). "The GIP staining in these patients was lower despite increased circulating GIP levels indicating increased K-cell turn-over in patients of acromegaly with diabetes." (PMID 30948746, 2019). "In vivo and in vitro studies support that diabetes results in elevated circulating peripheral dopamine, likely also derived from the gut, and is responsible for blocking GIP signaling and LOX levels in osteoblasts." (PMID 31687648, 2019). "We observed that both the number and intensity of GIP staining cells in the duodenal and colonic biopsies of patients of acromegaly with diabetes was significantly lower than the healthy controls." (PMID 30948746, 2019). "The majority of studies indicate that defective GLP-1 secretion does not appear to predate the development of glucose intolerance, rather diabetes itself seems to be associated with the acquired defect in GLP-1 secretion and GIP action." (PMID 31366085, 2019). "GIP administration, even at higher than normal physiological doses, did not stimulate insulin secretion in diabetic humans, indicating that diabetes in some way interferes with GIP signaling." (PMID 31687648, 2019). "Patients of acromegaly, irrespective of presence or absence of hyperglycaemia, had similar degree of insulin resistance, however patients with diabetes exhibited hyperglucagonemia, and compromised β-cell function despite significantly higher GIP levels." (PMID 30948746, 2019). "Our study also provides the first evidence of increased serum dopamine levels in diabetes, and further shows that dopamine inhibits GIP‐stimulated LOX expression in osteoblasts." (PMID 31687648, 2019). "The number and intensity of GIP secreting cells were higher in healthy controls as compared to patients of acromegaly with diabetes (p = 0.009 and 0.003, respectively)." (PMID 30948746, 2019). "In contrast, GIP is involved in energy storage and fat deposition, which when chronic, promotes diabetes development." (PMID 29324870, 2018). "DPP-4is is a new class of anti-diabetes which can prevent the rapid degradation of glucose-dependent insulinotropic polypeptide (GIP) and glucagon-like peptide 1(GLP-1) through inhibition of DPP-4, thus enhancing insulin secretion." (PMID 29206832, 2017). "GLP-1 and GIP can play a compensatory function of islet cell when islet cell function was gradually lost in diabetes." (PMID 28893239, 2017). "Compared to individuals in Q1 of GIP; PORs for diabetes were 4.0 (95% CI: 0.7–22.2), 4.2 (95% CI: 0.8–21.7) and 12.2 (95% CI: 3.3–77.2) (P for trend = 0.0003) for Q2, Q3 and Q4, respectively." (PMID 28753646, 2017). "It was reported that endogenous GIP plays a limited role in beta cell survival in STZ-induced diabetes models." (PMID 27053237, 2016). "GLP-1 and GIP levels are likely to be impaired in diabetes and the regulation of the GLP-1 and GIP secretion plays crucial role and represents a promising therapeutic strategy for diabetes." (PMID 27721485, 2016). "This increase in plasma concentration is similar to previous studies where a significant effect has been shown with GIP administration in both healthy individuals and in patients with diabetes." (PMID 25613747, 2015). "Transgenic pigs expressing a GIPRdn in their beta-cells mimic important aspects of human pre-diabetes: impaired function of the incretin hormone GIP, disturbed glucose tolerance, reduced insulin secretion, and progressive reduction of beta-cell mass." (PMID 25890210, 2015).